SPZ1 (spermatogenic leucine zipper 1)
Description:
Transcription factor that binds to the DNA sequence 5'-CANNTG-3'(E box) and the G-box motif. May play an important role in the regulation of cell proliferation and differentiation during spermatogenesis (By similarity).
Synonyms: NYD-TSP1; FLJ25709; PPP1R148; CILD38
Tractability: No criterion of Open Targets' tractability assessment is met for any kind of drug.
Gene: Protein-coding gene on chromosome 5 (80,319,625 to 80,321,842, forward strand). Ensembl gene ENSG00000164299.
Subcellular location: Cytoplasm; Nucleus
Subcellular location (Human Protein Atlas): Mid piece
Gene Ontology:
Molecular function: protein binding; DNA-binding transcription factor activity
Biological process: regulation of DNA-templated transcription
Cellular component: nucleus; cytoplasm
Genetic constraint (gnomAD): Loss-of-function variants: 0 observed, 0.6 expected, observed/expected ratio (o/e) 0, 90% interval 0 to 1.82. That is too few expected variants to judge how well the gene tolerates losing a copy. Missense variants: 384 observed, 470.08 expected, observed/expected ratio (o/e) 0.82, 90% interval 0.75 to 0.89. Synonymous variants: 150 observed, 161.09 expected, observed/expected ratio (o/e) 0.93, 90% interval 0.81 to 1.07.
Homologues: Orthologues: dog SPZ1 (56% identical), pig SPZ1 (55% identical), mouse Spz1 (43% identical), rat Spz1 (42% identical), tropical clawed frog mia3 (31% identical), Drosophila melanogaster Tango1 (14% identical). Paralogues in human: MIA3 (32% identical), MIA2 (17% identical), CTAGE1 (17% identical), CTAGE15 (15% identical), CTAGE8 (15% identical), CTAGE9 (15% identical), CTAGE4 (15% identical), CTAGE6 (15% identical), OTOR (2% identical), MIA (2% identical).
Diseases named in the same sentence as SPZ1 in open-access papers:
SPZ1 is named in the same sentence as 16 diseases in open-access papers, as found by Europe PMC text mining. Sharing a sentence is not in itself a finding about the gene and the disease. The quoted sentences say what the papers report.
liver cancer (3 papers, 2019 to 2022). An epithelial or non-epithelial malignant neoplasm that arises from the liver. "SPZ1 acetylation at K369 and K374 coupled with TWIST acetylation at K73 and K76 is required for SPZ1-TWIST1 complex formation, which promotes liver cancer metastasis." (PMID 35053509, 2022). "For example, Wang LT and colleagues found that SPZ1 promoted EMT and metastasis in liver cancer, specifically by trans-activating TWIST1, which encodes a master regulator of EMT." (PMID 34749766, 2021).
breast carcinoma (1 paper, 2021). "Moreover, SPZ1 overexpression in breast cancer promotes drug-resistance and metastases." (PMID 34749766, 2021).
colorectal cancer (1 paper, 2024). A primary or metastatic malignant neoplasm that affects the colon or rectum. "In our previous studies, we showed that SPZ1 contributes to the invasion and chemoresistance of breast cancer cells, and protects colorectal cancer cells against apoptosis 13,14." (PMID 39440046, 2024). "Furthermore, SPZ1 inhibits apoptosis of colorectal cancer cells, promotes proliferation, and enhances resistance to 5-fluorouracil 11,13,14." (PMID 39440046, 2024).
embryonic carcinoma (1 paper, 2022). "It has been revealed that a reduction in Spz1 levels based on RNA interference decreased embryonic carcinoma cell proliferation." (PMID 35574435, 2022).
gastric cancer (1 paper, 2021). A primary or metastatic malignant neoplasm involving the stomach. "Moreover, mechanistic investigations revealed that LINC01050 functions as a molecular sponge to absorb cytosolic miR-7161-3p, which reduces the miR-7161-3p-mediated translational repression of SPZ1, thus contributing to gastric cancer progression." (PMID 34749766, 2021).
hepatoma (1 paper, 2019). "Therefore, SPZ1 appeared to interact with TWIST1 in cultured hepatoma cells, SPZ1 transgenic mice, and HCC tumor specimens." (PMID 30154425, 2019). "Considering the high proliferation and metastatic rates of hepatoma cells induced by the SPZ1–TWIST1 axis, we next evaluated the potential effects of inhibitors or modulators of upstream (RTK signaling) or downstream (VEGF signaling involving the SPZ1–TWIST1 complex) pathways." (PMID 30154425, 2019). "In the present study, hepatoma cells treated with the TIP60 inhibitor TH1834 or transfected with the TWIST1 AC2 mutant showed loss of acetylation and nuclear localization of both TWIST1 and SPZ1." (PMID 30154425, 2019). "The interaction between SPZ1 and TWIST1 was further evaluated in tumors and adjacent healthy liver tissues from SPZ1 transgenic mice and patients with hepatocellular carcinoma (HCC)." (PMID 30154425, 2019). "Further, acetylation of SPZ1 induced by TIP60 leads to the formation of the SPZ1–TWIST1 complex and its nuclear translocation, which consequently activates VEGF expression in hepatoma cells." (PMID 30154425, 2019). "Aggressive hepatoma cells (SK-Hep1 and HA 22T), which express high levels of the VEGF protein, showed enhanced recruitment of the SPZ1–TWIST1 complex to the VEGF promoter compared with that observed in cells with low or no VEGF (Hep 3B and PLC, respectively) expression." (PMID 30154425, 2019).
infertile (1 paper, 2019). "Sox17 is detected in about 10% of all testis specific genes, and Spz1, a spermatogenic Zip regulatory Protein, is drastically reduced in meiotic cells of oligozoospermic infertile men." (PMID 31645906, 2019).
nasopharyngitis (1 paper, 2024). An inflammatory process that affects the nasopharynx. "The IHC scores of SPZ1 were significantly higher in the NPC samples compared to that in nasopharyngitis (NP) tissues." (PMID 39440046, 2024).
tumor (8 papers, 2014 to 2024). "There is growing evidence that cancer progression is associated with aberrant SPZ1 expression in tumor tissues 11,13,14,20." (PMID 39440046, 2024). "It has since been shown by Hsu and colleagues that SPZ1, which encodes a transcription factor, acts as a proto-oncogene to promote cellular proliferation and tumour formation in a mouse model." (PMID 25594029, 2014). "SPZ1 knockdown significantly decreased tumor volume and weight compared to that in the control group." (PMID 39440046, 2024). "Correspondingly, a significant strong association and higher expression have been revealed in a recent investigation of SPZ1 using in vitro and in vivo methods, demonstrating that SPZ1 contributes to tumor progression by inhibiting apoptosis." (PMID 35627192, 2022). "The expression of VEGF and that of the endothelial marker CD31 was determined in tumor tissues injected with SK-Hep1 cells expressing GFP-tagged SPZ1." (PMID 30154425, 2019). "In particular, the lysine residues K369 and K374 in SPZ1 were found to be critical for tumor growth, and this was confirmed using the AC mutant of SPZ1." (PMID 30154425, 2019). "VEGF expression was colocalized with ectopic SPZ1 expression in the tumor tissues, in contrast with the observations using mock-transfected or SPZ1 shRNA-transfected SK-Hep1 cells." (PMID 30154425, 2019). "In addition, IL-6 expression in the tumor tissues correlated positively with SPZ1 expression (R2 =0.6719)." (PMID 39440046, 2024). "SPZ1 is up-regulated in various human cancers and functions as a tumor promoter." (PMID 34749766, 2021). "Finally, in the present study, expression of the downstream oncogenic activator VEGF was upregulated by the SPZ1–TWIST1 complex through its interaction with BRD4 in tumor cells." (PMID 30154425, 2019). "In contrast to the original observation of proliferation regulation by its homodimer, SPZ1 activates and interacts with TWIST1 to form another functional bHLH dimer, which provides a plausible explanation for the mechanism by which SPZ1 transactivates TWIST1 expression during tumor progression." (PMID 30154425, 2019). "Higher CD31 expression was detected in a radial configuration in perivascular regions of tumor tissues injected with SK-Hep1 cells; conversely, tumor masses injected with SPZ1 shRNA-transfected SK-Hep1 cells showed a lower level and a more scattered pattern of CD31 expression." (PMID 30154425, 2019). "Therefore, SPZ1 is an important regulator of tumor metastasis and cell plasticity in the tumorigenic microenvironment." (PMID 30154425, 2019). "SPZ1 expression alone was shown to activate TWIST1 expression and initiate EMT, implying that SPZ1 may, to some extent, exert a regulatory effect on tumor progression induced by TWIST1 expression." (PMID 30154425, 2019). "Thus, we found that the B domain (bHLH domain) of SPZ1 may be critical for tumor growth, invasion, and metastasis in vivo, possibly through interaction with TWIST1." (PMID 30154425, 2019). "IL-6 silencing in NPC cells significantly impaired cell growth and proliferation, while exogenous IL-6 restored the malignant features of the SPZ1-knockdown NPC cells, indicating that IL-6 participates in SPZ1-mediated tumor progression." (PMID 39440046, 2024). "KAT5 was involved in HCC tumor cell growth and promoted EMT by acetylation of the SPZ1-TWIST1 complex." (PMID 34650217, 2021). "Our findings highlight the importance of acetylation signaling in the SPZ1–TWIST1–BRD4 axis in the mediation of EMT and its regulation during tumor initiation and metastasis." (PMID 30154425, 2019). "Along with the oncosuppression induced by the formation of complexes of TWIST1 with other epigenetic regulators, the acetylated SPZ1–TWIST1 complex activates VEGF expression, thus inducing changes in tumor cells and the tumor microenvironment." (PMID 30154425, 2019).
tumor (continued). "TWIST1 was shown to be expressed in invasive primary tumors in SPZ1 transgenic mice and in noninvasive neoplastic lesions, suggesting that TWIST1 exerts a positive regulatory effect on target genes involved in tumor initiation and progression." (PMID 30154425, 2019). "In addition, SPZ1 homodimers activate TWIST1 expression and are acetylated by TIP60 to form a heterodimeric SPZ1-TWIST1 complex, which promotes EMT and initiates tumor metastasis." (PMID 34749766, 2021). "Therefore, the SPZ1–TWIST1 complex appears to regulate VEGF expression and secretion, which consequently regulates angiogenesis in tumor masses." (PMID 30154425, 2019). "Confocal fluorescence imaging was used to examine the interaction between SPZ1 and TWIST1 in immunostained samples of tumor masses and adjacent healthy liver tissues from patients with HCC, showing TWIST1 protein expression (red) and SPZ1 expression (green) in HCC cells." (PMID 30154425, 2019). "Further, the SPZ1 homodimer activates TWIST1 expression and is acetylated by TIP60 forming the SPZ1–TWIST1 heterodimeric complex, which activates the expression of downstream EMT markers and initiates tumor metastasis." (PMID 30154425, 2019). "To replicate these findings in the context of cancer development and metastasis, we used IVIS imaging to evaluate tumor cell growth and metastasis in nude mice injected (via tail vein) with constitutively RFP-expressing SK-Hep1 cells expressing pEGFP, SPZ1-GFP, or SPZ1ΔB." (PMID 30154425, 2019). "Moreover, SPZ1 was shown to mediate EMT signaling and regulate tumor metastasis by transactivation of TWIST1 expression." (PMID 30154425, 2019). "TWIST1 overexpression alone or co-expression with SPZ1∆B in Hep 3B cells showing low SPZ1 expression did not significantly activate EMT markers' expression, indicating the importance of the SPZ1–TWIST1 complex in tumor cell metastasis." (PMID 30154425, 2019).
cancer (7 papers, 2010 to 2025). A tumor composed of atypical neoplastic, often pleomorphic cells that invade other tissues. "Among them, Spz1 whose binding sites were found in the –0.6 kb to -0.3 kb region, is expressed in several murine cancer cell lines and stimulates cell proliferation and tumorigenesis." (PMID 28207785, 2017). "Although functions of Fthl17 gene are so far unknown, the results suggest that Fthl17 is involved in cell proliferation through regulation by Spz1 and Plzf in cancer cells and in GSCs, respectively." (PMID 28207785, 2017). "Whereas FAC1 acts as the internal TF in 6 tissue-type TF-TF interaction networks from immune systems and cancer, SPZ1 mainly serves as the internal TF in tissue-type TF-TF interaction networks from testis, and the rest in 5 to 6 tissue-type TF-TF interaction networks from different tissue types." (PMID 20085649, 2010). "SPZ1 acts as a proto-oncogene and forms an SPZ1-TWIST1 complex through the acetylation of TWIST1 during tumorigenesis, which is essential for cancer cell migration." (PMID 41044669, 2025). "Here we report that the HIV-1 Tat-interacting protein 60 kDa (Tip60) acetyltransferase mediates acetylation at lysine residues of SPZ1 at positions 369 and 374, and of TWIST1 at positions 73 and 76, which are required for SPZ1–TWIST1 complex formation and cancer cell migration in vitro and in vivo." (PMID 30154425, 2019).
infection (2 papers, 2009 to 2021). The state of being infected such as from the introduction of a foreign agent such as serum, vaccine, antigenic substance or organism. "Subsequently, proHP6 activates proHP8, which activates Spz1 to bind to Toll and mediate the broad response to infection." (PMID 34639230, 2021).
SPZ1 also shares sentences with these, for which no sentence is quoted: nasopharyngeal carcinoma (1 paper); ovarian carcinoma (1); rectal cancer (1); rectum (1); rectum tumors (1).